ITGB4 (integrin subunit beta 4)
Diseases named in the same sentence as ITGB4 in open-access papers (continued):
Sharing a sentence is not in itself a finding about the gene and the disease.
colorectal cancer (21 papers, 2016 to 2025). A primary or metastatic malignant neoplasm that affects the colon or rectum. "Elevated expression of ITGB4 is associated with decreased overall survival in colorectal cancer and non-small cell lung cancer." (PMID 36385523, 2023). "Exosome-transmitted FOSL1 is attributed to oxaliplatin resistance in colorectal cancer via activation of ITGB4." (PMID 38814534, 2024). "Transcriptome analysis from The Cancer Genome Atlas (TCGA) pinpointed ITGB4 as a target gene in colorectal cancer, suggesting a critical role in disease development." (PMID 39169946, 2024). "Another recently published study did look at the relation between ITGB4 gene expression level and clinical outcomes of colorectal cancer patients." (PMID 35112314, 2023). "Meanwhile, ITGB4 can be used as a target site to form a lump in colorectal cancer, gastric cancer, prostate cancer, lung cancer, and other diseases to regulate the progress of diseases." (PMID 34485523, 2021). "Pursuing predictors of colorectal cancer, a growing number of studies have identified valuable biomarkers, such as Integrin beta-4 (ITGB4), Placenta-specific protein 1 (PLAC1), some miRNAs and lncRNAs." (PMID 35126454, 2021). "HiChIP data showed that ITGB4 is regulated by a colorectal-cancer-specific enhancer, and RNA-seq data showed that ITGB4 is upregulated (fold change = 2.31) in colorectal cancer tissue, suggesting the regulation of ITGB4 by colorectal-cancer-specific enhancers." (PMID 34361106, 2021). "Furthermore, elevated expression of both MMP15 and ITGB4 has been observed in colorectal cancer patients following radical surgery." (PMID 39169946, 2024). "TCN1 may play a carcinogenic role in colorectal cancer by regulating the ITGB4 signaling pathway leading to cytoskeleton damage and promoting cell death." (PMID 38035071, 2023). "Data in our study suggested that the upregulation of ITGB4 in colorectal cancer cells may due to the regulation of colorectal-cancer-specific enhancers." (PMID 34361106, 2021). "Aberrant ITGB4 expression has been reported in several cancers, including colorectal cancers." (PMID 34361106, 2021). "RNA-seq analysis has also shown the significant upregulation of ITGB4 in colorectal cancer tissue." (PMID 34361106, 2021). "ITGB4 maybe an early detector and a prognostic element for colorectal cancer." (PMID 34631528, 2021). "In conclusion, MDFI promotes the proliferation and tolerance to chemotherapy of colorectal cancer cells, partially through the activation of the AKT signaling pathway by the binding to ITGB4/LAMB3." (PMID 38375821, 2024). "In colorectal cancer (CRC), Transcobalamin 1 (TCN1) disrupts the cytoskeletal network through modulation of ITGB4 signaling." (PMID 39169946, 2024). "And ITGB4 is upstream of PI3K/AKT (as evidenced by the KEGG website), and the relationship between ITGB4 and the PI3K/AKT pathway has also been reported in renal cancer and colorectal cancer." (PMID 38982076, 2024). "ITGB4 was substantially expressed in single cells of basal cell carcinoma, cholangiocarcinoma (CHOL), colorectal carcinoma CCRC), glioma, HNSCC, non-small cell lung cancer (NSCLC), ovarian serous cystadenocarcinoma (OV), and pancreatic adenocarcinoma (PAAD)." (PMID 36076232, 2022). "In primary human colorectal cancer cells, the levels of both ITGA6 and β4 integrin subunit (ITGB4) subunits of the α6β4 integrin are increased." (PMID 29401653, 2018). "Along with similar results in colorectal cancer, these data suggest that FRA-1 might contribute to the transactivation of the ITGB4 promoter in invasive breast cancer, as previously shown in undifferentiated basal keratinocytes." (PMID 37176013, 2023).
lung carcinoma (21 papers, 2015 to 2024). "Solute carrier family 3 member 2 (SLC3A2) can associate with integrin-β chains like Integrin beta 4 (ITGB4) in lung cancer, thereby influencing integrin signaling, cell survival, and cell migration." (PMID 39228892, 2024). "The interaction between GRP78 and annexin A7 (ANXA7) was facilitated after the use of ZBM-H, which was accompanied by an increased phosphorylation of ITGB4, which in turn regulated lung cancer cell behavior." (PMID 39169946, 2024). "Conversely, in breast and lung cancers, ITGB4 correlates with the level of immune cell infiltration, suggesting potential roles in NA metabolism and protein processing within its functional mechanism." (PMID 39169946, 2024). "ITGB4 and urokinase-type plasminogen activator (uPA) encoded by PLAU, two common overregulated genes in lung cancer, promote angiogenesis via ERK1/2 phosphorylation, leading to cell growth." (PMID 39228892, 2024). "Our studies implicate that KCNF1 functions in the nucleus through a permeation-independent mechanism and promotes lung cancer by enhancing ITGB4 signaling." (PMID 36385523, 2023). "Our findings suggest that KCNF1 promotes lung cancer by enhancing ITGB4 signaling and implicate KCNF1 as a novel therapeutic target for lung cancer." (PMID 36385523, 2023). "Knockdown of ITGB4 increases cisplatin sensitivity in lung cancer models suggesting that ITGB4 is relevant for resistance to multiple chemotherapeutics." (PMID 37291514, 2023). "IHC results also confirmed that GALNT3, CYCS, EIF5A, and ITGB4 were highly expressed in lung cancer tissues than normal lung tissues." (PMID 35651789, 2022). "In lung cancer, ITGB4 might be related to leucine-rich repeat-containing protein 15 (LRRC15), which is involved in cell-cell and cell-matrix interactions and overexpressed in mesenchymal-derived tumors, exerting a metastatic invasion role in lung cancer." (PMID 39228892, 2024). "ITGB4 is aberrantly expressed in several cancers including breast, colorectal, and lung cancers." (PMID 38589501, 2024). "Increased expression of ITGB4 in lung cancer was correlates with poorer prognosis." (PMID 34222028, 2021). "CD166+, CD133+, CD44+, and CD24+ITGB4+NOTCHhi cells have been labeled as CSCs or TICs in different studies, but few of these studies could be repeated in lung cancer cell lines or samples." (PMID 25965829, 2015). "In lung cancer, KCNF1, a regulator of epithelial-mesenchymal transition (EMT) and ECM-integrin interactions, positively regulates signaling downstream of ITGB4." (PMID 39169946, 2024). "The transcription levels of ITGA11, ITGB4 and ITGB8 between lung cancer and normal samples in ONCOMINE database." (PMID 31875161, 2019). "Using ONCOMINE database, we investigated the transcription levels of ITGA11, ITGB4 and ITGB8 in lung cancer vs. normal samples." (PMID 31875161, 2019). "And the interaction of ITGB4 promoter with some transcription factors in other disease is also reported, such as KLF4 in glioma 21, RUNX1 in myeloid leukemia 22, ZEB1 in prostate cancer 23, TP73 in lung cancer 24, GLI1 in ovarian cancer 25, and JUN in pancreatic cancer." (PMID 31602273, 2019). "Furthermore, we analyzed ITGA11, ITGB4 and ITGB8 mRNA expression level in both lung cancer and normal tissues using the TCGA-LUAD and TCGA-LUSC original data." (PMID 31875161, 2019).
prostate carcinoma (21 papers, 2009 to 2025). A carcinoma that arises from epithelial cells of the prostate gland. "In hepatocellular carcinoma and prostate cancer, ITGB4 expression is associated with tumor-associated fibroblasts." (PMID 39169946, 2024). "ITGB4 has been implicated in various cancers, including prostate cancer, colorectal cancer, and lung cancer and may correlate with poor prognosis." (PMID 38172503, 2024). "Moreover, we could again confirm the inverse association of the ITGB4 level and number of tumor-associated leukocytes in prostate cancer samples." (PMID 36932441, 2023). "Moreover, it has been reported that the loss or dissociation of ITGB4, which leads to the breakup of the cell basement membrane, could be related to an increased risk of metastasis in prostate cancer." (PMID 37371594, 2023). "ITGB4 has emerged as a critical driver of metastatic tumor cell migration and invasion in prostate cancer, as evidenced by studies using DU145 cells." (PMID 39169946, 2024). "ITGB4 has also been shown to play a crucial role in the development of prostate cancer found that ITGB4 promotes prostate tumorigenesis by co-expression with ErbB2 and c-Met in tumor progenitor cells." (PMID 38172503, 2024). "Studies have found high levels of expression of ITGB4 in prostate cancer, where ITGB4 in prostate tumor progenitor cells amplifies ErbB2 and Met signaling transduction." (PMID 39239559, 2024). "Parathyroid hormone-related peptide (PTHrP) also contributes to prostate cancer growth and metastasis by regulating ITGB4 levels through transcriptional and post-translational pathways, including association with the NF-κB signaling pathway." (PMID 39169946, 2024). "In our analyses of clinical specimens, we observed a clear induction of ITGB4 during prostate cancer progression." (PMID 36932441, 2023). "Studies have shown that the decreased expression of ITGB4 and laminin-5 genes occurs during the progression of prostate intraepithelial neoplasia and the development of prostate cancer." (PMID 34485523, 2021). "In prostate cancer, ITGB4 appears to promote tumorigenesis by enhancing the signaling of the RTKs ErbB2 and c-Met in tumor progenitor cells." (PMID 31242404, 2020). "ITGB4 regulates the migration and invasion of prostate cancer." (PMID 39169946, 2024). "Interestingly, ITGB4 promoter methylation levels exhibit variation across prostate cancer cell lines representing distinct disease stages, including local tumors, lymph node metastases, and bone metastases." (PMID 39169946, 2024). "Furthermore, EPCAM, which mediates cell adhesion, and ITGB4, an integrin that can regulate cellular growth and movement, were downregulated in 3xR cells, and both have been shown to be overexpressed in prostate cancer and facilitate metastasis." (PMID 37870957, 2023). "In prostate cancer, the silencing of ITGB4 reduces the ability of tumor progenitor cells to self-renew in vitro, suggesting that ITGB4 signaling may play a critical role in maintaining CSCs within the tumor." (PMID 37371594, 2023). "While earlier studies reported reduced expression of ITGB4 in both prostatic intraepithelial neoplasms and invasive prostate carcinomas, later publications are available showing overexpression of ITGB4 in more aggressive prostate carcinomas." (PMID 36932441, 2023). "Based on our hypothesis that the leukocyte adhesion cascade is most important in the process of hematogenous metastasis, ITGB4 emerged as a possible driver of metastasis identified using the relatively E-/P-selectin-independent metastatic prostate cancer model." (PMID 36932441, 2023). "We compared the expression levels of eight integrin subunits (ITGA2, ITGA5, ITGAV, ITGB1, ITGB3, ITGB4, ITGB5, and ITGB6), HOXB13, HOXA11-AS, CCL2, CXCL12, and IBSP in prostate cancer tissues that had metastasized to bone, lymph nodes, lungs, liver, and other organs." (PMID 33514011, 2021).
prostate carcinoma (continued). "Furthermore, while ITGB4 is almost absent in the TCs of primary prostate cancer specimens, the percentage of ITGB4+ TCs drastically increases in locally advanced/recurrent tumors (treated with palliative transurethral resection, TURp), lymph node and distant metastases." (PMID 36932441, 2023). "One notable exception was prostate cancer in which neither of the PGCC signatures but rather the 5-gene core signature of late progeny (FN1, INPP5D, ITGB4, ARHGDIB, IFIT1) was significantly predictive of outcomes." (PMID 38447798, 2024).
triple-negative breast carcinoma (17 papers, 2020 to 2026). An invasive breast carcinoma which is negative for expression of estrogen receptor (ER), progesterone receptor (PR), and human epidermal growth factor receptor 2 (HER2). "For example, ITGB4+ cancer stem cells have an intermediate epithelial/mesenchymal phenotype and elevated ITGB4 was associated with worse relapse-free survival in triple-negative breast cancer (TNBC)." (PMID 38447798, 2024). "In triple-negative breast cancer, ITGB4 marks cancer stem cells in pEMT and was associated with reduced relapse-free survival following chemotherapy." (PMID 36076232, 2022). "Notably, overexpression of ITGB4 in triple-negative breast cancer cells has been implicated in the transfer of ITGB4 protein to cancer-associated fibroblasts (CAFs) via exosomes." (PMID 39169946, 2024). "For instance, ITGB4 promotes triple-negative breast cancer to resist DNA damage via TNFAIP2/IQGAP1/RAC1, and thus accelerates the drug resistance of tumor cells." (PMID 38831335, 2024). "Integrin beta 4 (ITGB4) is highly expressed on triple-negative breast cancer (TNBC) cells and their derived exosomes, and promotes glycolysis in CAFs through mitophagy." (PMID 36588730, 2022). "More recently, Bierie and colleagues used ITGB4 as a functional biomarker to classify more aggressive CSCs from other mesenchymal carcinoma cell subsets in triple-negative breast cancer." (PMID 34504657, 2021). "Integrin beta 4 (ITGB4)-overexpression in triple-negative breast cancer (TNBC) cells was found to provide the ITGB4 protein to the CAFs via exosomes, which induced BNIP3L-dependent mitophagy in CAFs, thereby increasing their glycolysis levels." (PMID 34373744, 2021). "It seems the case with breast-cancer-cell-secreted ITGB4 that it is mainly secreted by triple negative breast cancer cell lines, and more specifically by some of the lines of this molecular subtype." (PMID 33080792, 2020). "ITGB4 promotes triple-negative breast cancer (TNBC) drug resistance via TNFAIP2/IQGAP1/RAC1." (PMID 37787041, 2023). "In addition, integrin beta 4 (ITGB4)-overexpressing triple-negative breast cancer (TNBC) cells provide the cancer-promoting capabilities of CAFs with ITGB4 proteins via exosomes, thus enhancing BNIP3L-dependent mitophagy and producing more lactate in CAFs." (PMID 38067169, 2023). "One of the molecular mechanisms proposed for this resistance in mesenchymal-like triple-negative breast cancer cells is due to the expression of ITGB4 + in intermediate states, regulated by Zeb1 through its repression on Tap63α expression, a protein that promotes ITGB4 expression." (PMID 34003341, 2021). "ITGB4 interacts with TNFAIP2 and promotes triple-negative breast cancer (TNBC) drug resistance and DNA damage repair." (PMID 37787041, 2023). "A recent study has shown that triple negative breast cancer cells can induce CAF glycolytic switch and mitophagy via exosome-mediated integrin ITGB4 export that induces ITGB4 expression by CAFs themselves." (PMID 33080792, 2020).
pancreatic cancer (15 papers, 2016 to 2025). "In pancreatic cancer, increased ITGB4 expression implies enhanced invasiveness, is associated with molecular features indicative of epithelial-mesenchymal transition (EMT), and independently predicts poor outcome." (PMID 36932441, 2023). "To further confirm the role of ITGB4 phosphorylation at Y1510 in ITGB4-mediated cell signaling in pancreatic cancer, we introduced a mutation of tyrosine to alanine at the position 1510 (Y1510A) of ITGB4." (PMID 31242404, 2020). "We found that both ITGB4 and p-ITGB4-Y1510 were highly expressed in pancreatic cancer tissues, and the higher ITGB4 expression was significantly associated with poor survival of patients with pancreatic cancer." (PMID 31242404, 2020). "We demonstrated that ITGB4 and its phosphorylated form are not only responsible for the regulation of pancreatic cancer cell migration and invasion, but are also associated with poor survival of pancreatic cancer patients." (PMID 31242404, 2020). "As to integrins, ITGA6 and ITGB4 are integrins that are highly expressed in pancreatic cancer stem‐like cells, contributing to tumor aggressiveness, treatment resistance, and metastatic dissemination." (PMID 40952239, 2025). "In pancreatic cancer cells, autophagy is linked to Integrin Subunit Beta 4 (ITGB4)‐ BCL2 interacting protein 3 (BNIP3) expression, with ITGB4/BNIP3 activation promoting MHC‐I engulfment by autophagosomes, aiding immune evasion." (PMID 40673641, 2025). "Subcutaneous tumour graft and orthotopic tumour experiments in mice showed that downregulation of ITGB4 significantly enhanced the therapeutic effect of PD‐1 antibodies on pancreatic cancer." (PMID 40673641, 2025). "Higher mRNA levels of ITGB6 and ITGB4 were detected in pancreatic cancer patients with higher histologic grades." (PMID 37779898, 2023). "As seen for PC-3 tumors, KD of ITGB4 in human pancreatic cancer cells (PaCa5061) significantly impaired s.c. xenograft tumor growth in WT Pfp−/−/Rag2−/− mice." (PMID 36932441, 2023). "To further explore the biological function of ITGB4 in pancreatic cancer, we analyzed cell migration by scratch assay in pancreatic cell lines PC-1.0 and AsPC-1." (PMID 31242404, 2020). "Taken together, these results indicate that ITGB4 not only functionally participates in the migration and invasion of pancreatic cancer cells, but it also regulates the MEK1-ERK1/2 signaling cascade through its phosphorylation at Y1510." (PMID 31242404, 2020). "We analyzed the expression of ITGB4 and p-ITGB4-Y1510 in pancreatic cancer tissue and cell lines using immunohistochemistry, Western blot, or semi-quantitative reverse transcription PCR." (PMID 31242404, 2020). "Overall, our study showed that ITGB4 and its phosphorylated form promote cell migration and invasion in pancreatic cancer and that p-ITGB4-Y1510 regulates the downstream MEK1-ERK1/2 signaling cascades." (PMID 31242404, 2020). "ITGB4 and p-ITGB4-Y1510 were highly expressed in pancreatic cancer (n = 176) compared with normal pancreatic tissue (n = 171)." (PMID 31242404, 2020). "The inhibition of phosphorylation of ITGB4 at Y1510 in pancreatic cancer PC-1.0 and AsPC-1 cells significantly decreased the level of p-MEK1 (T292) and p-ERK1/2 but did not affect the level of p-MEK1 (T386) and p-MEK2 (T394)." (PMID 31242404, 2020). "The inhibition of ITGB4 expression by siRNA indeed suppressed pancreatic cancer cell migration and invasion, indicating that ITGB4 plays a pivotal role in the malignancy of pancreatic cancer." (PMID 31242404, 2020). "In this study we investigated the role of integrin β4 (ITGB4) and its phosphorylation at tyrosine Y1510 (p-ITGB4-Y1510) in the tumorigenesis of pancreatic cancer." (PMID 31242404, 2020). "In summary, these results indicate that ITGB4 plays an important role in the migration and invasion ability of pancreatic cancer cells." (PMID 31242404, 2020).